EGFR (epidermal growth factor receptor)
Diseases named in the same sentence as EGFR in open-access papers (continued):
Sharing a sentence is not in itself a finding about the gene and the disease.
breast carcinoma (continued). "Both agents have demonstrated in vitro and in vivo efficacy against HER2- and EGFR-amplified breast cancer cell lines, with neratinib demonstrating significantly lower IC50 values in cell line models." (PMID 31141894, 2019). "Data from our laboratory showed an increased expression of EGFR in HER2-overexpressing breast cancer cells that had acquired resistance to trastuzumab." (PMID 30736768, 2019). "Studies have indicated that EGFR and c-Src contribute to the aggressive phenotype in various human cancers, especially breast cancer." (PMID 31430896, 2019). "In fact, overexpression of Cdc42 in breast cancer is mainly mediated by cell surface receptors (such as epidermal growth factor receptor (EGFR)) or some oncogenes." (PMID 30754684, 2019). "The cytotoxic activity and percentage inhibition of compounds 5–18 on EGFR against MDA-MB-231 breast cancer cell line." (PMID 31074303, 2019). "EPA and DHA are expected to prevent breast cancer by decreasing epidermal growth factor receptor and human epidermal growth factor-2 signaling which reduce proliferation." (PMID 30803190, 2019). "It is believed that the cross-talk between EGFR and ERα plays a critical role in the regulation of breast cancer development." (PMID 31737560, 2019). "Rather, we focused on how EGFR activation (using EGF as stimuli) influences breast cancer cell glucose metabolism." (PMID 31532771, 2019). "The target compounds 5a, 5b, 5d–g and 5k that showed potent anticancer activity against MCF-7 breast cancer cell line were tested for their inhibitory activity against EGFR." (PMID 30919701, 2019). "We engineered EGFR and Her2/neu reactive hemibodies and an EGFR-specific BiTE control and tested their abilities to redirect T cells to the dual antigen-positive breast cancer cell line MDA-MB-231." (PMID 31772172, 2019). "Another study has revealed that Polygonatum odoratum lectin induces apoptosis and autophagy by targeting EGFR-mediated RAS/RAF/MEK/ERK pathway in human MCF-7 breast cancer cells." (PMID 30858760, 2019). "EGFR, HER2, HER3 and HER4 gene alterations, including copy number variation, mutation and mRNA dysregulation, in patients with breast cancer and TNBC, were analyzed." (PMID 30658422, 2019). "Several molecules targeting EGFR/HER2 signaling (downstream of IL-8) have been intensively investigated in breast cancer." (PMID 31330794, 2019). "Antibodies targeting specific tumor-associated antigens like epidermal growth factor receptor (EGFR) and human epidermal growth factor two (HER2) are increasingly used to treat solid tumors (respectively colorectal cancer and breast cancer)." (PMID 30984170, 2019). "The involvement of human epidermal growth factor receptor (EGFR) and c-Src in breast cancer has been examined." (PMID 31430896, 2019). "Peptidyl-tyrosine modification and peptidyl-tyrosine phosphorylation refer to role of EGFR in breast cancer." (PMID 34466490, 2019). "Here, we explored the cellular mechanism and signaling pathways that can explain the relation between EGFR and breast cancer cell glucose metabolism." (PMID 31532771, 2019). "Another example of reduced colony size was reported after combined MEK and EGFR/HER2 inhibition in breast cancer cells." (PMID 30673853, 2019). "The tyrosine phosphorylation of EGFR was ablated in GRB7 knockdown ERBB2+ breast cancer, suggesting the effects of Grb7-mediated EGFR activation on the malignancy of ERBB2+ breast cancer." (PMID 31083325, 2019). "Since HER2-positive breast cancer cell lines express also at least one other member of HER receptor family particularly EGFR and HER3." (PMID 30884851, 2019). "For example, exosomes from parental cells engineered to an EGFR-specific peptide ligand were successfully targeted to xenograft EGFR+ breast cancer cells in mice." (PMID 32009978, 2019).
breast carcinoma (continued). "The growth suppressing effect of CB1 receptor is due to a down-regulation of the epidermal growth factor receptor (EGFR) in prostate cancer cell lines or via the activation of cAMP/protein kinase A pathway in breast cancer cells." (PMID 31121931, 2019). "We found that iEFs downregulated EGFR activation and also prevented formation of actin-rich filopodia in breast cancer cells in the presence of EGF." (PMID 31428691, 2019). "Although there is no evidences showing EGFR overexpression and corticotroph tumor aggressiveness till now, EGFR overexpression predicted tumor progression and poor prognosis in breast cancer and prostate Cancer." (PMID 31798535, 2019). "As the translational clinical medicine research displayed that high expression of EGFR is closely related to the malignant degree of breast cancer and leading to metastasis and poor prognosis." (PMID 30957572, 2019). "Human breast cancer cells sense the stiffness of ECM through EGFR (also known as human epidermal growth factor (HER-2)) and integrin to activate Src family kinases (SFK)." (PMID 31438519, 2019). "For example, copy number gain of SYNJ2 in breast cancer leads to EGFR activation by altered trafficking pathways." (PMID 31073965, 2019). "These 111In-hEGF-BCMs showed EGFR density-dependent cellular uptake and nuclear importation in a panel of human breast cancer cell lines (MDA-MB-468, MDA-MB-231 and MCF-7)." (PMID 31659527, 2019). "Prior studies showed that E2 promotes brain metastatic colonization of a brain-tropic subline of human TN MDA-MB-231 breast cancer cells (231BR) via paracrine activation of EGFR." (PMID 30796353, 2019). "In one breast cancer cell with high amplification of EGFR, sensitivity to its target drug, Gefitinib, was much higher than that in the other breast cancer cells, suggesting a possible correlation between EGFR-copy-gain and sensitivity to Gefitinib." (PMID 31480645, 2019). "3MC was able to trigger the co-immunoprecipitation of GPER, AHR and EGFR, thus generating a ternary complex assembly of these receptors in SkBr3 breast cancer cells toward their functional cooperation." (PMID 31370872, 2019). "Recently, a link between environmental chemicals such as Bisphenol A and cancer progression has been suggested in ER-negative in flammatory breast cancer cells, in which EGFR/ERK signaling was involved." (PMID 31737560, 2019). "It is upregulated by EGFR in the TNBC cell line MDA-MB-231 and is associated with lymph node metastasis in breast cancer patients." (PMID 31139569, 2019). "Collective expression of breast cancer cell surface markers (EpCAM, EGFR, and HER2) using a cocktail of target-specific antibodies was assessed." (PMID 30871481, 2019). "Our group recently showed in breast cancer patients that EGFR expression is strongly correlated with high tumor uptake of the glucose analogue, 18F-fluorodeoxyglucose (FDG)." (PMID 31532771, 2019). "We previously reported the design of a kit for labelling DTPA-hEGF with 111In for AE radiotherapy of EGFR-positive breast cancer." (PMID 31659527, 2019). "High expression levels of KLF5 are a determinant of resistance to cisplatin in ovarian and breast cancers and corresponded with enhanced EGFR signaling in both colorectal cell lines." (PMID 30478887, 2019). "This is the case with p130Cas activation of downstream p38/MAPK as a result of mechanically-activated integrin and EGFR in breast cancer cells." (PMID 31438519, 2019). "We built gene interaction network for 30 targets associated with breast cancer and observed ER1, EGFR, and SRC were the strongest effector for the relationship." (PMID 30906412, 2019). "We report here the first study to examine the modulation of gene regulation by EGFR/HER2 in a clinically relevant HER2+ breast cancer cell line." (PMID 30736768, 2019).
breast carcinoma (continued). "This study demonstrated that EGFR stimulation dose- and time-dependently augmented T47D breast cancer cell glucose uptake in a manner accompanied by increased lactate production, thus indicating enhanced glycolytic flux." (PMID 31532771, 2019). "G Protein Coupled Receptors crosstalk with receptor tyrosine kinases such as EGFR, which are overexpressed in breast cancers." (PMID 31208996, 2019). "Such a mechanism was shown for breast cancer where responses to chemotherapy were much stronger in tumors with activated EGFR when followed by administration of an EGFR‐targeting drug." (PMID 30499260, 2019). "In conclusion, we identified a novel signaling pathway of EGF-mediated up-regulation of PN-1 in breast cancer cells, which requires cascade activation of EGFR/PKCδ/MEK/ERK/EGR1, which was crucial for breast tumor metastasis and BCSC stemness." (PMID 31501409, 2019). "Various substrates of PTPN2 play important roles in the genesis and progression of breast cancer amongst others the epidermal growth factor receptor (EGFR), STAT3, and proposedly the Met receptor." (PMID 31025094, 2019). "We identified EE02 as an EGFR/Eps8 complex inhibitor that demonstrated promising antitumor effects in breast cancer and NSCLC." (PMID 31118055, 2019). "For targeted in vivo imaging of epidermal growth factor receptor (EGFR)-overexpressing cancer cells, Herceptin-conjugated MnO was injected i.v. into a mouse-bearing breast cancer brain metastatic tumor." (PMID 31315232, 2019). "Binding and internalisation of 111In-EGF-AuNPs by breast cancer cells was EGFR-dependent and was 12-fold higher for MDA-MB-468 than MCF-7 human breast cancer cells with high or low EGFR expression, respectively." (PMID 31659527, 2019). "EGFR itself has previously been reported to also localise to the nucleus in human squamous carcinoma and breast cancer cells." (PMID 31747426, 2019). "In the current study, a new liposome, 111In-EGF-LP-Dox, was designed for chemo-radionuclide therapy of EGFR-positive cancer and the use of US-induced cavitation to enhance its delivery to breast cancer tumour models was investigated." (PMID 31534505, 2019). "In SKBR3 breast cancer cells, K19 is required for Src activity downstream of EGFR to drive cell proliferation." (PMID 31126068, 2019). "Curcumin inhibited the growth and proliferation of breast cancer cells by reducing EGFR signaling and decreasing EGFR and Akt levels." (PMID 31590362, 2019). "Treatment of cancer cell lines (A431 epidermoid carcinoma, MDA-MB-231 breast carcinoma) with gefitinib (EGFR inhibitor) or camptothecin (topoisomerase inhibitor) triggered apoptosis, as evidenced by elevated levels of cleaved caspase-3." (PMID 30778617, 2019). "The EGFR transactivation by estrogen via the GPER has been proposed as an alternate signaling pathway with a potential significance for breast cancer." (PMID 30646517, 2019). "Using a mouse model of breast cancer metastasis, in vivo and ex vivo imaging showed that both EGFR and αvβ3 integrin-targeting were required to reliably direct the nanoparticle to metastasis and capture the spread and exact topology of the disease." (PMID 31356633, 2019). "Although dual EGFR/HER2 tyrosine kinase inhibitor lapatinib has provided effective clinical benefits for HER2-positive breast cancer patients, acquired resistance to this drug remains a major concern." (PMID 31569723, 2019). "EGFR activation has been shown to increase IL-1 ligand expression via increased NFkB activity in breast cancer cells resulting in increased growth and invasion." (PMID 31320902, 2019). "For example, miR-133a-3p suppresses tumor cell invasion and migration by targeting Fascin1 (FSCN1) and regulates the cell cycle and proliferation of breast cancer cells by targeting epidermal growth factor receptor (EGFR)." (PMID 31660998, 2019).
breast carcinoma (continued). "CBD can also inhibit the growth and metastasis of breast cancer cells through the epidermal growth factor (EGF)/epidermal growth factor receptor (EGFR) and protein kinase B (AKT)/mTOR/4EBP1 signaling pathways." (PMID 31349651, 2019). "Breast cancer cells highly express EGFR, but adhere less to the collagen-coated surface compared to normal cells, suggesting lesser mechanosensing ability of the cancer cells compared to normal cells." (PMID 31438519, 2019). "Combination of OC as a c-Met inhibitor with the dual HER2/EGFR inhibitor LP induced synergistic growth inhibition for the mitogen-mediated growth of HER2-positive breast cancer cells in vitro and in vivo." (PMID 30781364, 2019). "They showed that the EVs conjugated with RNA nanoparticles harboring EGFR aptamer, loaded with survivin siRNA, were able to inhibit breast cancer growth in mice." (PMID 30991632, 2019). "NK-92 cells and primary NK cells were engineered to express the second generation of EGFR-CAR to target breast cancer cells." (PMID 30805309, 2019). "EE02 selectively suppressed growth and induced apoptosis in EGFR-positive and Eps8-positive breast cancer and NSCLC cells." (PMID 31118055, 2019). "The EGFR expression level in MDA-MB-231 cells was relatively higher compared with other breast cancer cells." (PMID 31214503, 2019). "This study is aimed to determine the downstream effects on transcription following EGFR upregulation in HER2+ breast cancer cells." (PMID 30736768, 2019). "The effect of EB and DAPT in regulating the expressions of EGFR and Notch signaling pathway in breast cancer cells and tumor tissues were measured by western-blot assay." (PMID 30957572, 2019). "In conclusion, EGFR activation shifts T47D breast cancer cell glucose metabolism toward glycolytic flux by upregulating hexokinase activity and GLUT-1 expression." (PMID 31532771, 2019). "EGFR is often overexpressed in breast cancer, especially in triple-negative breast cancer 37, while hypermethylation of EGFR can contribute to cetuximab resistance." (PMID 31777591, 2019). "The silencing of ORAI3 attenuated hypoxia-associated phosphorylation of the EGF receptor (EGFR) and the expression of genes associated with cell migration and inflammatory/immune responses in the MDA-MB-468 model of basal breast cancer." (PMID 30754719, 2019). "Recently, it was found that verrucarin A induces ROS levels in breast cancer MDA-MB-231 cells resulting in the activation of p38-MAPK and the inhibition of EGFR/Akt/ERK signaling cascade to cause cell deaths." (PMID 31772936, 2019). "We also found the overexpression of EGFR was positively correlated with PN-1 expression in breast cancer cells and tissues." (PMID 31501409, 2019). "Human breast cancer cell lines with high and low EGFR expression (MDA-MB-468 and MCF7 respectively) were used to study selectivity of liposomal uptake, subcellular localisation of drug payload, cytotoxicity and DNA damage." (PMID 31534505, 2019). "Previously, we showed that the EGFR is upregulated in trastuzumab resistant HER2 positive (HER2+) breast cancer cells." (PMID 30736768, 2019). "Further studies are needed to define the therapeutic value of TrkB and EGFR inhibition for breast cancer BM." (PMID 30796353, 2019). "We demonstrated a tumor-suppressive function of CGRRF1 in breast cancer and identified EGFR as its target." (PMID 31801577, 2019). "Collectively, EGF/EGFR/AJAP1 axis controled breast cancer tumor progression and metastasis by mediating the β-catenin nuclear transactivation." (PMID 31171012, 2019). "For example, in basal‐like breast cancer, specific lncRNAs correlate with the activation of epidermal growth factor receptor‐dependent pathways and EMT." (PMID 30499165, 2019).
breast carcinoma (continued). "In 2007, success of the Phase III clinical trial, NCT00078572, led to the FDA approval of lapatinib in combination with capecitabine for treatment-naïve, ER+/EGFR+/HER2+ breast cancers." (PMID 30975211, 2019). "Human epidermal growth factor receptor 2 (HER2), a target used in breast cancer treatment, is the second member of the epidermal growth factor receptor (EGFR) family and is a type of receptor tyrosine kinase." (PMID 31296222, 2019). "An LDH release assay also revealed that the cytotoxic effects of EGFR-specific CAR-T cells increased when an activator was used to promote EGFR dimerization as compared to untreated breast cancer cells." (PMID 31804974, 2019). "The protein EGFR is a representative cooperator of c-Src in a regulatory mechanism of breast cancer." (PMID 31430896, 2019). "Breast cancer initiation and progression is triggered by certain cellular downstream signaling pathways which are initiated by the activation of ERα, PR, EGFR and HER-2 receptors." (PMID 31673107, 2019). "Altogether, our results indicate that GPER is involved in a transduction network that includes AHR and EGFR toward 3MC-induced stimulatory effects in breast cancer cells." (PMID 31370872, 2019). "FASN, prominent in various cancer types, can increase expression of epidermal growth factor receptor (ErbB) that promotes EMT of breast cancer cells and invasive ductal carcinomas." (PMID 31849832, 2019). "This study definitively shows that the MMTV-Wnt1 mouse model produces two phenotypically distinct subtypes of mammary tumors that differ in multiple biological aspects including sensitivity to an EGFR inhibitor." (PMID 31213486, 2019). "Considering breast cancer, high levels of the EGFR and c-erbB2 correlate with poor prognosis because of a high incidence of metastases and intrinsic resistance." (PMID 30975222, 2019). "In another in vitro comparative study authors employed 30 nm Au NPs conjugated with mAbs (panitumumab), which target breast cancer (BC) cells overexpressing EGFR." (PMID 31434562, 2019). "The HER2-E breast tumors are driven by HER2/EGFR signaling, such as it showed, through a silico and omyc analyses, in the TCGA breast cancer project." (PMID 31737566, 2019). "We demonstrated that TGF‐β treatment induced a significant increase in EGFR expression in breast cancer cells, and EGFR was essential for TGF‐β‐induced enhancement of the migration and invasion abilities of breast cancer cells." (PMID 29215776, 2018). "High EGFR expression is correlated with the aggressiveness of cancer and the poor prognosis of patients with breast cancer." (PMID 29215776, 2018). "SphK1 product S1P can initiate tyrosine phosphorylation of EGFR in breast cancer cells, which was consistent with the observations previously reported in vascular smooth muscle cells and fibroblasts." (PMID 29385066, 2018). "It has been reported that BPA at low concentrations causes an increase in epidermal growth factor receptor (EGFR) activation and the downstream ERK pathway in inflammatory breast cancer cells, which is associated with increased cell proliferation." (PMID 30065191, 2018). "Most studies were done on breast cancer detection focusing on EGFR (epidermal growth factor receptor)." (PMID 30410710, 2018). "In fact, there are some breast cancer cell lines that have expression levels of EGFR lower than that of KYSE14020." (PMID 30104638, 2018). "Dysregulated EGFR signaling has been observed in many cancer types, including breast cancer, colon cancer, and lung cancer." (PMID 29215776, 2018). "To support these observations, we showed that TGF‐β enhances the migration ability of breast cancer cells, increases EGFR expression, and activates the MAPK signaling pathway." (PMID 29215776, 2018). "Epidermal growth factor receptors (EGFR) not only influence the estrogen pathway and regulate breast cancer cell survival and spreading, but also influence the SphK1 network." (PMID 29385066, 2018).